CLDN7 (claudin 7)
Description:
Plays a major role in tight junction-specific obliteration of the intercellular space.
Synonyms: CLDN-7; CEPTRL2; CPETRL2; Hs.84359; claudin-1
Tractability: Antibody: UniProt places it where antibodies can reach, with high confidence; its Gene Ontology location is reachable by antibodies, with high confidence; UniProt predicts a signal peptide or a membrane-spanning region. PROTAC: ubiquitination databases record sites on it.
Gene: Protein-coding gene on chromosome 17 (7,259,347 to 7,264,016, reverse strand). Ensembl gene ENSG00000181885.
Subcellular location: Cell membrane; Basolateral cell membrane; Cell junction, tight junction
Subcellular location (Human Protein Atlas): Vesicles; Cell Junctions
Pathways (Reactome):
Cell-Cell communication: Tight junction interactions
Developmental Biology: Epithelial-Mesenchymal Transition (EMT) during gastrulation
Gene Ontology:
Molecular function: protein binding; identical protein binding; structural molecule activity
Biological process: calcium-independent cell-cell adhesion; cell-cell junction organization
Cellular component: basolateral plasma membrane; cell junction; plasma membrane; bicellular tight junction; apicolateral plasma membrane; lateral plasma membrane; membrane
Genetic constraint (gnomAD): Loss-of-function variants: 15 observed, 19.28 expected, observed/expected ratio (o/e) 0.78, 90% interval 0.52 to 1.2. The upper end of that interval is the gene's LOEUF score, 1.2, which puts it in group 5 of 6, group 1 being the genes least tolerant of losing a copy. Missense variants: 261 observed, 287.96 expected, observed/expected ratio (o/e) 0.91, 90% interval 0.82 to 1. Synonymous variants: 117 observed, 111.64 expected, observed/expected ratio (o/e) 1.05, 90% interval 0.9 to 1.22.
Homologues: Orthologues: chimpanzee CLDN7 (99% identical), macaque CLDN7 (97% identical), dog CLDN7 (93% identical), rat Cldn7 (93% identical), mouse Cldn7 (92% identical), rabbit CLDN7 (91% identical), pig CLDN7 (91% identical), guinea pig CLDN7 (80% identical), tropical clawed frog cldn7 (64% identical), zebrafish cldn7b (61% identical). Paralogues in human: CLDN1 (61% identical), CLDN19 (54% identical), CLDN3 (46% identical), CLDN9 (45% identical), CLDN14 (44% identical), CLDN4 (44% identical), CLDN6 (44% identical), CLDN5 (43% identical), CLDN8 (42% identical), CLDN17 (38% identical), CLDN2 (38% identical), CLDN20 (37% identical), and 10 more.
Diseases named in the same sentence as CLDN7 in open-access papers:
CLDN7 is named in the same sentence as 116 diseases in open-access papers, as found by Europe PMC text mining. Sharing a sentence is not in itself a finding about the gene and the disease. The quoted sentences say what the papers report.
breast carcinoma (39 papers, 2005 to 2026). "Low expression of Claudin-3, Claudin-4, and Claudin-7 (CLDN3, CLDN4, and CLDN7) is associated with 3 types of epithelial cancers: breast cancer (BRCA), STAD, and bladder cancer (BLCA)." (PMID 41082105, 2026). "The risk score of breast cancer prognosis was determined with the following formula: RiskScore = 0.629*ANO6 + 0.147*CELSR3 + 0.381*CLDN7+ 0.273*EPB41L4B-0.357*FAM166B -0.843*GPLD1–0.202*LEF1–0.202*PPARG -0.127*SUSD3." (PMID 34364397, 2021). "In colorectal cancer, increased claudin 7 expression has been associated with disruption of cell polarity, proliferation and tumor growth, both in vivo and in vitro, being in line with our breast cancer results." (PMID 29482498, 2018). "Down-regulation of claudins has also been reported in some other epithelial tumors, including loss of claudin-1 in breast cancer and colonic cancer, as well as the loss of claudin-7 in breast cancer and head and neck cancer." (PMID 24073219, 2013). "Loss of claudin-7 expression is significantly correlated with high histological grade of breast carcinoma, including ductal carcinoma in situ and invasive ductal carcinoma." (PMID 24009024, 2013). "Downregulation of CLDN7 has been linked to breast cancer as well as invasiveness of both endometrial cancer and esophageal squamous cell carcinoma, while the upregulation of CLDN7 has been found in ovarian cancer, chromophobe renal cell carcinoma, and gastric cancer." (PMID 38540693, 2024). "Interestingly, hypermethylation has be implicated in the downregulation of CLDN7 expression in breast cancer and two transcription factors, Tcf-4 and Sox9, have been shown to cooperate in CLDN7 repression in colon cells." (PMID 21789222, 2011). "In support of these findings, loss or decreased expression of CLDN7, which is expressed constitutively during mammary epithelium development, has been significantly associated with higher histological grade, loss of cellular cohesion, and increased metastasis in breast carcinoma." (PMID 22616718, 2012). "Claudin-7 expression was shown to be lower in high grade breast carcinomas and decreased expression was found in ER- tumors." (PMID 39687048, 2024). "The low expression of CLDN7 was found to be correlated with breast cancer grade and metastasis as well as colon cancer progression." (PMID 31998788, 2020). "It has been reported that recovery of various claudin proteins expression, such as CLDN3, CLDN4, and CLDN7, can reduce the malignant behavior of cancer cells and reduce the invasiveness in breast cancer." (PMID 29221203, 2017). "As other authors have identified low expression of claudin 7 as being a characteristic feature of CL tumors, we examined the expression of claudin 7 across the breast cancer subtypes in our in silico database." (PMID 28045912, 2017). "These claudin-7 KD cells displayed the severe cell-matrix adhesion defect that was also observed in breast cancer cell line T-47D." (PMID 26081244, 2015). "As expected, epithelial genes known to be inactivated during EMT in breast cancer cells, such as Cdh1 (E-cadherin), Ocln (Occludin), Epcam, Cldn7 (Claudin 7), Id1, Krt7, Esr1, Cav2, Dsp, Gata3, and Cadm1 were among the downregulated genes." (PMID 25674539, 2015). "Gene expression analysis also suggested decreased expression of adhesion molecules such as cadherin-related family member 3, CD226, Claudin 7 and Ocludin, upon breast cancer cells exposure to LDL." (PMID 24428917, 2014). "Aberrant localisation of Claudin 7 to the cytoplasm has been shown to occur in breast cancer cells and oesophageal squamous cell carcinoma." (PMID 24358122, 2013). "DNA hypermethylation is associated with the downregulation of CLDN11 in gastric cancer cells and CLDN7 in breast cancer cells." (PMID 24009024, 2013). "They find that claudin-7 is down-regulated in head and neck cancer, nasopharyngeal cancer, squamous cell carcinomas of the oesophagus and in breast cancer." (PMID 21310043, 2011).
breast carcinoma (continued). "To set the stage for functional experiments on this molecule, we examined the developmental expression and localization of claudin 7 in the murine mammary epithelium and in a selection of murine mammary tumors." (PMID 15743505, 2005). "Furthermore, CLDN7, a tight junction protein, suppresses breast cancer invasion and metastasis through the repression of the smooth muscle actin program." (PMID 41301179, 2025). "In addition, lentivirus claudin-7 shRNA was used to knockdown claudin-7 expression in breast cancer cell line T-47D (right)." (PMID 26081244, 2015). "In light of this data, CLDN7 has been proposed as a breast cancer tumor-suppressor gene." (PMID 22616718, 2012). "In addition to estrogen signaling and resistance to therapy, 7 of the identified genes have been previously associated with cell cycle regulation (CCND1, CDKN1A, CDKN1B, and CDKN2A) and breast cancer aggressiveness (CLDN7 and DLC1)." (PMID 22616718, 2012). "In breast cancer, claudin-7 expression was also found to be decreased and inversely correlated with tumor grade and metastatic disease, although there is evidence that claudin-7 may become re-expressed in metastases." (PMID 21789222, 2011). "Sukumar and colleagues reported that claudin 7 was localized to tight junctions of the human mammary carcinoma cell line MCF-7 by using an antibody directed toward the cytoplasmic tail of the human protein, which differs by one amino acid from the mouse protein." (PMID 15743505, 2005). "These same authors found, similarly to our observations with EPH4 cells, that claudin 7 colocalized with ZO1 in MCF7 breast cancer cells and could also be observed in cytoplasmic spots." (PMID 15743505, 2005). "Breast cancer cell lines reflective of the CL subtype were also found to express low or absent levels of the epithelial cell-cell adhesion proteins examined (E-cadherin, claudin 3, claudin 4 and claudin 7) and markers of breast luminal epithelial cell differentiation (ER, PR and HER-2)." (PMID 28045912, 2017). "Likewise, reduced claudin-7 levels correlates with the histological grading of breast carcinomas." (PMID 21310043, 2011). "Interestingly, the murine tumors showed claudin 7 expression at the mRNA level equal to or higher than that of the lactating mammary gland, where the largest proportion of the cells are the luminal epithelial cells that give rise to mammary tumors." (PMID 15743505, 2005). "For example, CLDN1, CLDN3, CLDN7, CLDN16 and CLDN20 have been found to be downregulated in breast cancer, and the downregulation of these claudins appearing to be linked to a more aggressive phenotype and with poor clinical outcome." (PMID 38137355, 2023). "The significant DEGs (CLDN7, BMPER, FGF7, MSRB3) in breast cancer samples compared to normal samples also showed coincident results of significant gene identification." (PMID 34151730, 2021). "In the analysis of the correlation between overall survival and significant DEG expression (CLDN7, MLLT10, RBM33, SH3RF1, SSBP4, and UBE2Z) in breast cancer, we found a shorter survival time based on GSE5881 and GSE42568 (P< 0.05)." (PMID 34151730, 2021). "A putative correlation (p = 0.05 in univariate analysis) has been previously reported between membranous claudin 7 and RFS in a cohort of 75 breast carcinomas." (PMID 29482498, 2018). "The claudin-low subtype is a recently identified molecular subtype of human breast cancer characterized by low expression of tight junction and adherens genes including CLDN3, CLDN4, CLDN7 and CDH1." (PMID 24009024, 2013). "Furthermore, in breast cancer, LSD1 can repress the expression of the tight junction protein claudin-7 (CLDN7)." (PMID 36879346, 2023). "Previous studies have shown that CLDN2, CLDN6 and CLDN7 are involved in patient response to chemotherapies in cancers including breast cancer and colorectal cancer, yet with no clear mechanism identified." (PMID 38137355, 2023).
breast carcinoma (continued). "Overall, these analyses of this set of clinical data showed a negative correlation of expression of CYP1B1 and CLDN7 in breast cancer, consistent with our findings in CL TNBC." (PMID 36077068, 2022). "Significantly overexpressed genes (CLDN7, MLLT10, RBM33, SH3RF1, SSBP4, and UBE2Z) were correlated with shorter survival, whereas underexpressed genes (BMPER, FGF7, MSRB3, and TNRC6B) were correlated with longer survival in breast cancer." (PMID 34151730, 2021). "In some studies claudin-3 and -4 are overexpressed in breast cancer and in contrast, claudin-1 and claudin-7 are down regulated, or, completely absent." (PMID 26083392, 2015). "Using this approach we determined that claudin-low breast cancer is typically negative for ER, PR, HER2, claudin 3, claudin 4, claudin 7 and E-cadherin." (PMID 28045912, 2017). "Both RJ348 and RJ423 cells expressed only extremely low levels of Cldn3, Cldn4 and Cldn7 (data not shown) suggesting that both RJ348 and RJ423 cells share features of human claudin-low breast cancers." (PMID 28423599, 2017).
colorectal cancer (34 papers, 2007 to 2025). A primary or metastatic malignant neoplasm that affects the colon or rectum. "Claudin 7 expression is associated with better prognosis in colorectal cancer patients and induction of epithelial differentiation in colorectal cancer cells." (PMID 37998722, 2023). "Loss of claudin-7 has been reported to correlate with venous invasion and liver metastases in colorectal cancer." (PMID 32850397, 2020). "Similarly, EpCAM and claudin-7 associated via intracellular cytoplasmic tails in pancreatic adenocarcinoma and colorectal cancer cells." (PMID 32091301, 2020). "In colorectal cancer (CoCa) EpCAM is frequently associated with claudin-7." (PMID 25514462, 2015). "Indeed, in colorectal carcinoma, EpCAM and claudin-7 are found in association with the tetraspanins CD9 and/or CO-029 and promote metastasis formation." (PMID 21789222, 2011). "In addition, Claudin-7 was shown to be associated with CD44 in colorectal cancer cells." (PMID 30874545, 2019). "Claudin 7 mRNA expression was a predictor of RFS in patients with CMS2 colorectal cancers, with patients with low expression presenting a better RFS." (PMID 37998722, 2023). "Overexpression of SOX9 in an inducible SOX9 colorectal cancer cell model suppresses claudin 7 expression." (PMID 37998722, 2023). "The downregulation of Claudin-7 induces metastasis and invasion in colorectal cancer via the promotion of EMT." (PMID 37799140, 2023). "CLDN7 expression is downregulated as colorectal cancer tissue differentiation grade decreases, the invasion and migration abilities of colorectal cancer cells are subsequently enhanced as a result of modulation of CLDN7 expression." (PMID 36620607, 2022). "The expression of Cldn7 and Sox9 showed an opposite pattern in four colorectal cancer cell lines and the Cldn7 interference cell line." (PMID 34281572, 2021). "Low expression of the Cldn7 protein is found in a variety of malignant tumours, such as lung cancer, breast cancer, pancreatic cancer, and colorectal cancer (CRC)." (PMID 34281572, 2021). "In contrast, CLDN7 functions as a potential tumor suppressor and is found to be downregulated in colorectal cancer and metastasis." (PMID 34571860, 2021). "There is ample evidence for the complex of cell adhesion molecules, EpCAM and claudin-7, and a tetraspanin, promoting colorectal cancer progression." (PMID 32091301, 2020). "The evaluation of colorectal cancer and liver metastasis patients showed that complex formation of the EpCAM, claudin-7, CO-029, and CD44v6 was correlated with clinical data." (PMID 32091301, 2020). "These proteins interacting with claudin-2 were often over expressed or activated in colorectal cancer (A ∩ E) but only Smad4 was the proteins that interacted with claudin-7 (A ∩ E)." (PMID 28698546, 2017). "Claudin-7 expression is negatively regulated by Wnt/Tcf signaling via Sox-7 in colorectal cancer cells." (PMID 24009024, 2013). "Reduced expression of claudin-7 has been correlated with tumor invasion and metastasis in squamous cell carcinoma of the esophagus and in colorectal cancer." (PMID 21789222, 2011). "Specifically, the association of Fusobacteria with Cldn7 suggests a potential role in tight junction destabilization, while its correlation with Klf3 points to its involvement in WNT/β-catenin pathway dysregulation in colorectal cancer." (PMID 40427657, 2025). "In the realm of prognosis, high CLDN2 in colorectal cancer, high CLDN6/9 in endometrial cancer, or low CLDN7 in various cancers could inform risk stratification and follow-up intensity." (PMID 40687428, 2025). "However, the CLDN1 OE is shown to induce epithelial-to-mesenchymal metastasis, while CLDN7 acts as a tumor suppressor in colorectal cancer." (PMID 39175074, 2024).
colorectal cancer (continued). "From a clinical point of view, high CLDN2 in colorectal cancer appears to be linked to poor outcome in those receiving 5-FU treatment and CLDN1 and CLDN7 appear to form a claudin signature to predict the clinical response to chemotherapies in colorectal cancer." (PMID 38137355, 2023). "This interaction has not previously been assessed, but since previous evidence from colorectal cancer models suggests that claudin 7 promotes EMT, Sip1 may here be a connecting factor." (PMID 29482498, 2018). "Furthermore, claudin-7, CD44 variant 6, EpCAM and the tetraspanin CP-029 appear to be upregulated in colorectal cancer with liver metastasis and form a common complex in regions termed tetraspanin-enriched membrane microdomains (TEM)." (PMID 26243458, 2016). "Claudin-7 overexpression in colorectal cancer cells disrupts cell polarization, enhances β-catenin/Tcf activity and cell proliferation, and thereby promotes tumor formation in vivo in xenograft mice injected with claudin-7 overexpressing colorectal cancer cells." (PMID 24009024, 2013). "In addition, CLDN7 downregulation may promote invasion and metastasis of colorectal cancer, and was positively correlated with the depth of invasion, lymphatic vessel invasion and lymph node metastasis in esophageal squamous cell carcinoma." (PMID 36672179, 2023). "In addition to a structural role in tight junctions, claudin 7 also participates in signal transduction that may mediate a tumor suppression function in colorectal cancer." (PMID 37998722, 2023). "Additionally, claudin-7 has been shown to complex with a CD44 in colorectal cancer cells." (PMID 23521713, 2013). "This underscores how the balance of different claudins (CLDN1 vs CLDN7) influences tumor behavior: CLDN1 up and CLDN7 down defines a particularly aggressive colorectal cancer phenotype." (PMID 40687428, 2025). "In contrast, well-differentiated colorectal cancer cell lines HT-29 and DLD-1 undergo dedifferentiation upon knockdown of claudin 7 and acquire features of EMT." (PMID 37998722, 2023). "Claudin-7 (CLDN7) is aberrantly expressed in some types of cancers including gastric cancer, human clear cell renal cell carcinoma and colorectal cancer." (PMID 34364397, 2021). "The mRNA level of claudin-7 (CLDN7) was determined in samples from 18 healthy individuals, 100 individuals with dysplasia and 121 colorectal cancer patients using quantitative real time RT-PCR." (PMID 21310043, 2011). "In addition, claudin 7 expression is influenced by the activity of the WNT/TCF4 pathway in colonic epithelium and colorectal cancers in a manner that depends on the presence of transcription factor SOX9." (PMID 37998722, 2023). "Our findings revealed that the mRNA expression levels of CLDN1, CLDN2, CLDN12, and CLDN14 were upregulated in colorectal cancer tissues relative to normal tissues in the Oncomine database, whereas CLDN3, CLDN5, CLDN7, CLDN8, CLDN11, CLDN15, and CLDN23 were downregulated, as previously reported." (PMID 35281827, 2022). "However, when comparing colorectal cancer tissues from the GEPIA database to normal colonic mucosa, the mRNA level expression of CLDN3, CLDN7, and CLDN23 was shown to be significantly higher in these tumor tissues." (PMID 35281827, 2022). "In colorectal cancer, the correlation between claudin-7 expression and metastasis is also not clear." (PMID 26243458, 2016). "In colorectal cancer cells, WNT/TCF4 activation in the absence of SOX9 leads to high claudin 7 expression, which has diffuse localization in the basolateral membrane and favors loss of polarity." (PMID 37998722, 2023).